RSPO3 (R-spondin 3)
Description:
Activator of the canonical Wnt signaling pathway by acting as a ligand for LGR4-6 receptors, which acts as a key regulator of angiogenesis. Upon binding to LGR4-6 (LGR4, LGR5 or LGR6), LGR4-6 associate with phosphorylated LRP6 and frizzled receptors that are activated by extracellular Wnt receptors, triggering the canonical Wnt signaling pathway to increase expression of target genes. Also regulates the canonical Wnt/beta-catenin-dependent pathway and non-canonical Wnt signaling by acting as an inhibitor of ZNRF3, an important regulator of the Wnt signaling pathway. Acts as a ligand for frizzled FZD8 and LRP6. May negatively regulate the TGF-beta pathway. Acts as a key regulator of angiogenesis by controlling vascular stability and pruning: acts by activating the non-canonical Wnt signaling pathway in endothelial cells (By similarity). Can also amplify Wnt signaling pathway independently of LGR4-6 receptors, possibly by acting as a direct antagonistic ligand to RNF43 and ZNRF3.
Synonyms: PWTSR; THSD2; FLJ14440; CRISTIN1
Tractability: Antibody: a drug acting on it is in phase 2 or 3 trials; its Gene Ontology location is reachable by antibodies, with high confidence; UniProt places it where antibodies can reach, with medium confidence; UniProt predicts a signal peptide or a membrane-spanning region.
Gene: Protein-coding gene on chromosome 6 (127,118,663 to 127,199,481, forward strand). Ensembl gene ENSG00000146374.
Subcellular location: Secreted
Pathways (Reactome):
Gene expression (Transcription): RUNX1 regulates transcription of genes involved in WNT signaling
Signal Transduction: Regulation of FZD by ubiquitination
Gene Ontology:
Molecular function: signaling receptor binding; frizzled binding; heparin binding
Biological process: positive regulation of Wnt signaling pathway; blood vessel remodeling; positive regulation of canonical Wnt signaling pathway; positive regulation of non-canonical Wnt signaling pathway; positive regulation of Wnt signaling pathway, planar cell polarity pathway; sprouting angiogenesis
Cellular component: extracellular region; non-collagenous component of interstitial matrix
Genetic constraint (gnomAD): Loss-of-function variants: 16 observed, 32.35 expected, observed/expected ratio (o/e) 0.49, 90% interval 0.33 to 0.75. The upper end of that interval is the gene's LOEUF score, 0.75, which puts it in group 3 of 6, group 1 being the genes least tolerant of losing a copy. Missense variants: 275 observed, 320.18 expected, observed/expected ratio (o/e) 0.86, 90% interval 0.78 to 0.95. Synonymous variants: 103 observed, 108.4 expected, observed/expected ratio (o/e) 0.95, 90% interval 0.81 to 1.12.
Homologues: Orthologues: chimpanzee RSPO3 (97% identical), macaque RSPO3 (97% identical), pig RSPO3 (94% identical), dog RSPO3 (92% identical), rabbit RSPO3 (92% identical), mouse Rspo3 (89% identical), rat Rspo3 (88% identical), guinea pig RSPO3 (81% identical), tropical clawed frog rspo3 (62% identical), zebrafish rspo3 (50% identical). Paralogues in human: RSPO1 (42% identical), RSPO2 (40% identical), RSPO4 (32% identical).
Diseases named in the same sentence as RSPO3 in open-access papers:
RSPO3 is named in the same sentence as 95 diseases in open-access papers, as found by Europe PMC text mining. Sharing a sentence is not in itself a finding about the gene and the disease. The quoted sentences say what the papers report.
colon cancer (24 papers, 2012 to 2025). "For example, Wnt5a has been shown to decrease Lgr5/RSPO3 expression and β-catenin activity in vitro, and its expression has been associated with improved survival in colon cancer." (PMID 41008809, 2025). "RSPO2 and RSPO3 mutations are found in approximately 10% of colon cancers and occur in a mutually exclusive manner with APC mutations." (PMID 37048063, 2023). "Targeting RSPO3 in colon tumors with RSPO fusions promoted differentiation and loss of stem-cell function." (PMID 30872643, 2019). "In just one year after the initial discovery of RNF43 mutations in IPMN and MCN, recurrent RSPO2 and RSPO3 translocations were identified in 3.0% and 8.0% of colon cancer, respectively." (PMID 27338477, 2016). "RSPO1 stimulation of LGR4 potentiates Wnt signaling which is generally oncogenic, and overexpression of RSPO2 and RSPO3 is associated with carcinogenesis in human colon cancer as well as in mouse models of breast and colon cancer." (PMID 24205130, 2013). "However, a study of an Rspo3 overexpression model showed that Rspo3 overexpression can cause the occurrence and development of colon cancer by excessively activating the WNT pathway." (PMID 34099046, 2021). "The over-expression of RSPO3 in colon cancer is due to RSPO3 fusion as a result of DNA translocation." (PMID 39125653, 2024). "In the Malmö-CC cohort, IHC analysis revealed significantly elevated protein levels of RSPO3 in colon cancer tissues in comparison with normal colon mucosa." (PMID 37998393, 2023). "It was found that overexpression of RSPO2 and RSPO3 was presented by 4-10% of colon subjects and recurrent R-spondin fusions in colon cancer activate the Wnt signaling and increase the tumorigenesis." (PMID 37228491, 2023). "To explore this last finding further, we investigated how Foxy5 treatment affected the RSPO3 mRNA and RSPO3 protein levels in colon cancer tissues from our xenograft mouse model." (PMID 37998393, 2023). "Based on the elevated levels of both LGR5 and RSPO3 in colon cancer tissues, we performed an analysis that revealed positive correlations between RSPO3 and LGR5 at both the protein and mRNA levels." (PMID 37998393, 2023). "Expression of WNT5A (a tumor suppressor) negatively correlated with that of LGR5/RSPO3 (tumor promoters) in colon cancer cohorts." (PMID 37998393, 2023). "As therapeutic anti‐RSPO antibodies already exist and anti‐RSPO3 has been demonstrated to be well tolerated in a clinical trial for colon cancer, realistic and relatively fast opportunities lie ahead to explore RSPO targeting in breast cancer patients." (PMID 36106661, 2022). "First, RSPO2 and RSPO3 gene fusions with concomitant enhanced expression have been identified in colon cancer patients, and proposed as an alternative driver of Wnt/β-catenin hyperactivation that earmarks cancer in the colorectal tract." (PMID 34663878, 2021). "Tumor homeostasis was dysregulated by anti-Rspo3 plus taxane treatment and the combination enriched for differentiated colon tumor cells and reduced the frequency of cells with tumorigenic properties." (PMID 29127379, 2017). "Consistent with the qPCR data, in situ hybridization (ISH) analyses of primary human colon tumors indicated that RSPO3 expression was primarily in stromal cells." (PMID 29127379, 2017). "It was also the only receptor that was consistently expressed in colon tumors with RSPO2 or RSPO3 gene fusions." (PMID 24205130, 2013). "Remarkably, recurrent, gain-of-expression gene fusion of RSPO2 (to EIF3E) and RSPO3 (PTPRK) were found in ~10% of human colon cancers." (PMID 24205130, 2013). "used RNA-SEQ to analyze 70 pairs of colon cancer tumors and their adjacent non-cancer tissues and identified a plurality of fusion transcripts involving RSPO2 and RSPO3, where the two transcriptions appeared together in patients with colon cancer in colon cancer." (PMID 36645115, 2023).
colon cancer (continued). "Additionally, WNT974 treatment regressed murine intestinal tumours harbouring either Rspo2 or Rspo3 fusion mutations, whilst another PORCNi suppressed the growth of RSPO3-mutant patient-derived colon cancer organoids in a xenograft model." (PMID 37048063, 2023). "Indeed, the expression of RSPO2 and RSPO3 in colon tumor samples containing such fusions is significantly elevated compared with tumor samples without the fusions." (PMID 27338477, 2016). "In addition, RSPO2 and RSPO3 mRNAs are significantly overexpressed in a subset of colon cancer." (PMID 37998393, 2023). "Indeed, recurrent activating RSPO2 and RSPO3 gene fusions were found to occur in 10% of human colon tumors and a recent follow-up study targeting RSPO3 in a RSPO3-fusion tumor xenograft model was shown to downregulate genes expressed in the stem cell compartment and inhibit tumor growth." (PMID 27046199, 2016). "The demonstration that RSPO3 is a driver of intestinal cancer, and the fact that LGR5 is a WNT/β-catenin signaling target urged us to explore a possible relationship between RSPO3 and LGR5 as well as WNT5A signaling in colon cancer tissues." (PMID 37998393, 2023). "Originally in colon cancer, but also later in other cancer types, the RSPO2 and RSPO3 gene fusion product has been reported to correlate with a poor prognosis and survival." (PMID 37998393, 2023). "These reduced expression levels of LGR5 and RSPO3 occurred in parallel with reduced expression levels of unphosphorylated (active) β-catenin and its downstream target VEGFA in colon cancer cells." (PMID 37998393, 2023). "Both in vitro experiments in human-colon cancer cell line HT-29 and in vivo experiments in CRISPR-based xenograft mice provided the evidence that RSPO3 fusion gene was involved in the initiation and development of CRC via activating WNT signaling." (PMID 36129915, 2022). "In colon cancer, RSPO2 and RSPO3 gene fusions have been proposed to potentiate Wnt/β‐catenin signaling, providing a mutational alternative for classical APC and CTNNB1 mutations." (PMID 36106661, 2022). "By comparing with these 65 mRNAs, RSPO3 (ENSG00000146374.12) and SFRP4 (ENSG00000106483.10) in matrix CML(0.7) were found to be related to the occurrence of colon cancer." (PMID 33836755, 2021). "These included an ovarian tumor with RSPO1, pancreatic and colon tumors with RSPO2, and lung and CRC tumors with RSPO3 overexpression." (PMID 34663878, 2021). "In this study, we explored a possible relationship between the expression of WNT5A, a favorable prognostic factor in colon cancer, and the β-catenin signaling modulators LGR5 and RSPO3, which are also negative prognostic factors in colon cancer." (PMID 37998393, 2023). "Interestingly, none of the colon cancer cell lines expressed significant levels of RSPOs while previous published results showed HeLa cells express high levels of RSPO3." (PMID 22615920, 2012). "Furthermore, the fact that RSPO3 fusions have not been reported in other cancers suggest that this particular phenomenon may be specific to colon cancer." (PMID 30987640, 2019).
colorectal cancer (19 papers, 2014 to 2026). A primary or metastatic malignant neoplasm that affects the colon or rectum. "Moreover, a gain in RSPO2 or RSPO3 levels is evident in a subpopulation of colorectal cancer patients, caused either by stromal overexpression or by specific gene fusions, among which EIF3E–RSPO2 and PTPRK–RSPO3 occur mutually exclusively with classical APC and CTNNB1 driver mutations." (PMID 36106661, 2022). "Therefore, overexpression of RSPO3 and loss of PTPRK could confer a double hit in colorectal cancer (CRC) harboring the RSPO3-PTPRK fusion." (PMID 34585724, 2021). "PTPRK is a candidate tumor suppressor in mouse intestinal tumorigenesis as per insertional mutagenesis, and is a gene fusion partner with the oncogene RSPO3 in colorectal cancers." (PMID 31934854, 2020). "Translocations where the signal sequence or part of the extracellular domain of PTPRK is fused to RSPO3 are recurrent events in a subset of colorectal cancers." (PMID 31934854, 2020). "Most reports on the role of RSPO3 in cancer are derived from observations in colorectal cancer, where aberrant RSPO3–PTPRK fusions were detected." (PMID 30987640, 2019). "Rspo3 is highly expressed in colorectal cancer and plays a critical role in the self-renewal of intestinal stem cells and colorectal CSCs, and its blockade antibody has effective intervention on colorectal CSCs and colorectal tumors." (PMID 30310855, 2018). "Recent studies have reported that LGK974 and RSPO3 antibodies may be beneficial at in vitro and in vivo levels, however, the development of targeted therapeutics for colorectal cancer patients with P:R fusions is still in its infancy." (PMID 36129915, 2022). "To test whether PORCN inhibition causes a decrease in HR and FA genes in additional Wnt‐addicted cancer models, we examined RNA‐seq data from a colorectal cancer patient‐derived xenograft (CRC PDX) with a RSPO3 translocation that was treated with ETC‐159." (PMID 33660437, 2021). "Moreover, specific gene fusions result in its promoter driving the expression of oncogenic RSPO3 in a subset of colorectal cancers." (PMID 30924770, 2019). "Indeed, colorectal cancers with RSPO3 fusion are sensitive to RSPO3 antibody and porcupine inhibitor." (PMID 27338477, 2016). "RSPO2 and RSPO3 translocations appear to be mutually exclusive with APC mutations, consistent with the idea that the Wnt/β–catenin pathway needs to be activated one way or another in colorectal cancers." (PMID 25208913, 2014). "Notably, RSPO2 and RSPO3 are overexpressed by chromosome translocations in a subset of colorectal cancers; this translocation product markedly stimulates Wnt/β-catenin signalling." (PMID 25208913, 2014). "The second group features R-spondin 3 (Rspo3), collagen and calcium binding EGF domains 1 (Ccbe1), and Shisa homolog 3 (Shisa3) genes, potentially relevant to colorectal cancer and therapy." (PMID 41262530, 2026). "The oncogenic role of RSPO3 has been most extensively studied in colorectal carcinoma (CRC)." (PMID 30987640, 2019). "In colorectal cancer (CRC), WNT pathway activation by genetic rearrangements of RSPO3 is emerging as a promising target." (PMID 28100566, 2017). "TOPflash assays were performed in 293T cells with or without exogenous Wnt3a and R-spondin 3 (i.e., Wnt pathway on or off), as well as in HCT116 colorectal cancer cells with constitutively active Wnt signaling." (PMID 37011861, 2023).
prostate carcinoma (10 papers, 2011 to 2025). A carcinoma that arises from epithelial cells of the prostate gland. "Antagonists of both these genes, R-Spondin 2 (RSPO2) and R-Spondin 3 (RSPO3) fusions potentiate the Wnt/β-catenin signaling and have been linked with prostate cancer." (PMID 35201496, 2021). "RSPO3 levels are lower in prostate cancer than normal prostate, with a tendency for further loss in metastatic disease." (PMID 30987640, 2019). "In order to characterize the functional consequences of RSPO3 loss, we obtained a panel of prostate cancer cell lines (DU145, 22RV1, LnCaP, C4-2, PC3)." (PMID 30987640, 2019). "One of the strengths of our study, thus, is a demonstration of consistent RSPO3 loss between normal prostate to prostate cancer, as well as a significant trend of decreased biochemical relapse-free survival with lower levels of RSPO3 expression in multiple patient cohorts." (PMID 30987640, 2019). "RSPO3 down regulation is involved in prostate cancer invasiveness and interacts with the inflammatory mediator IL-1β." (PMID 37226243, 2023). "Of note, upregulation of RSPO3 mRNA was also observed in prostate cancer stroma, thus the role of RSPO3 during prostate cancer is unclear, with evidence pointing towards cell-type-specific functions." (PMID 35204808, 2022). "In combination with our functional in vitro and ex ovo investigations, our data strongly support a tumour-suppressor role for RSPO3 in human prostate cancer." (PMID 30987640, 2019). "In this report, we show that RSPO3 expression is lower in prostate cancer versus normal tissue, and that lower levels of RSPO3 prognosticate reduced biochemical relapse-free survival in several patient cohorts." (PMID 30987640, 2019). "We compare the relative levels of RSPO3 expression between normal prostate tissue and prostate cancer in two independent patient cohorts (Taylor and GSE70768—Cambridge)." (PMID 30987640, 2019). "Together, our preclinical findings identify a role of RSPO3 downregulation in prostate cancer invasiveness, and provide a potential explanation for how RSPO3 functions as a positive prognostic marker in prostate cancer." (PMID 30987640, 2019). "Despite these reports on a variety of cancers, studies on a potential role of RSPO3 in prostate cancer are conspicuously missing." (PMID 30987640, 2019). "RSPO3 levels are lower in prostate cancer samples compared to healthy prostate samples in several patient cohorts, and lower levels of RSPO3 prognosticate poorer biochemical relapse-free survival in these cohorts." (PMID 30987640, 2019). "Furthermore, given the previous findings in lung adenocarcinoma, we limited our search to datasets containing survival information for a possible correlation of RSPO3 expression with prostate cancer survival outcomes." (PMID 30987640, 2019). "Using these data, we compared RSPO3 expression between benign prostate tissue and prostate cancer." (PMID 30987640, 2019). "The mechanistic basis for RSPO3 biology in prostate cancer, however, is still much less clear." (PMID 30987640, 2019). "For elucidation of the biological effect of RSPO3, we use siRNA technology to reduce the levels of RSPO3 in established prostate cancer cell lines, and perform in vitro proliferation, invasion, western blotting for EMT markers and clonogenic survival assays for radiation resistance." (PMID 30987640, 2019). "Taken together, our results strongly suggest a tumour-suppressor role for RSPO3 in prostate cancer." (PMID 30987640, 2019). "Similar to our in vitro experiments, 22RV1.shRSPO3 cells displayed higher rates of extravasation in CAM assay compared to 22RV1.shCtrl cells (5.7 ± 1.0% versus 15.0 ± 1.9% extravasation; a 2.6-fold increase), further supporting a tumour-suppressor role for RSPO3 in prostate cancer." (PMID 30987640, 2019). "Module 2 includes TGFBR3, FOXO1, RSPO3, PLAG1, and CYLD, which have been shown to play a role in mediating or inhibiting prostate cancer progression." (PMID 39347576, 2024).
prostate carcinoma (continued). "All this suggests that it is unlikely that JMJD2D impinges in a meaningful way on the oncogenic potential of prostate cancer cells through modulating the expression of GLIS3, RSPO3, NPR1 or OSR2." (PMID 38045004, 2023). "Collectively, our results support a role for RSPO3 in mediating EMT and invasiveness in prostate cancer." (PMID 30987640, 2019). "This would be consistent with the notion that methylation of JMJD2D could promote prostate cancer development through upregulation of CBLC and METTL27 as well as through downregulation of COL4A5, GLIS3, NPR1, OSR2, PLAGL1 and RSPO3." (PMID 38045004, 2023). "In contrast to breast tumor stroma, the stromal reaction to invasive prostate cancer displayed fewer genes involved in tissue remodeling but a higher number of genes belonging to defined signaling pathways, including members of the Wnt signaling pathway (SFRP1, RSPO3)." (PMID 21611158, 2011). "However, a role for RSPO3 in prostate cancer prognosis and behaviour has not been explored." (PMID 30987640, 2019).